STAT3 (signal transducer and activator of transcription 3)
Diseases named in the same sentence as STAT3 in open-access papers (continued):
Sharing a sentence is not in itself a finding about the gene and the disease.
cancer (continued). "The powerful message of the newest results is that STAT3 is involved in the time-honored characteristic of cancer cells, dependence on glycolytic energy derivation." (PMID 21149895, 2010). "Our data demonstrated that FLLL32 was more potent than curcumin to inhibit STAT3 phosphorylation and STAT3 DNA binding activity, downregulate STAT3 target genes, and induce cancer cells apoptosis." (PMID 20712901, 2010). "Dually phosphorylated STAT3 present in cervical precancer and cancer lesions was found to localize to the nuclei and possessed a functional DNA-binding activity." (PMID 20977777, 2010). "STAT3 can promote immune tolerance in the setting of cancer and thus represents an attractive target to enhance immunotherapy." (PMID 20576164, 2010). "Collectively, our data show that Stat3 is one of the pivotal factors contributing to the regulation of autocrine production of IL-6 in cancer cells." (PMID 21122157, 2010). "HPV16+ cervical precancer and cancer tissues expressed a higher level of STAT3 and pSTAT3(Y705) as compared to that in the HPV- precancer and cancer lesions." (PMID 20977777, 2010). "Our data suggest that constitutively active STAT3 can act as a central mediator of aerobic glycolysis, which would explain the general STAT3 addiction of cancer cells." (PMID 21084727, 2010). "Previous studies have shown that STAT3 is a key mediator of critical cancer cell processes, as it promotes cell cycle progression and survival, stimulates angiogenesis and generally promotes malignant transformation." (PMID 20723213, 2010). "FLLL32 was also more potent than four previously reported JAK2 and STAT3 inhibitors as well as curcumin to inhibit cell viability in these cancer cells." (PMID 20712901, 2010). "FLLL32 was more potent than curcumin and other reported JAK2/STAT3 inhibitors in the inhibition of cancer cell viability in our comparisons." (PMID 20712901, 2010). "STAT3 is over-phosphorylated in most cancers, preventing apoptosis and enhancing proliferation, angiogenesis, and invasion." (PMID 20955590, 2010). "Present study demonstrated a significant correlation between HPV16 positivity and overexpression of STAT3 and pSTAT3 in cervical precancer and cancer lesions." (PMID 20977777, 2010). "Targeting Signal Transducer and Activator of Transcription 3 (STAT3) signaling is an attractive therapeutic approach for most types of human cancers with constitutively activated STAT3." (PMID 20712901, 2010). "The pleiotropic cytokine interleukin-6 (IL-6) is a major activator of Stat3; IL-6 stimulates the formation of tyrosine-phosphorylated Stat3 (p-Stat3) in cancer cells." (PMID 20482858, 2010). "Activated Stat3 has been shown to mediate migration of cancer cells by regulating genes such as integrin β6, tenascinC, twist and liv1." (PMID 20929542, 2010). "So while a STAT3 cancer connection has been extensively documented, what precisely does STAT3 do to promote or sustain cancer?" (PMID 21149895, 2010). "In contrast to moderate immunopositivity in precancer lesions, more than 70% cancer biopsies examined expressed moderate to high levels of STAT3 which was supported by both pSTAT3 IHC as well as immunoblotting." (PMID 20977777, 2010). "The role of STAT3 in cancer progression has been known for sometime, and its role in CSC regulation has only recently been investigated." (PMID 20929579, 2010). "Stat3 has critical roles in cancer cell proliferation and survival and its constitutive activation is associated with a number of human tumors." (PMID 20421975, 2010). "In comparison, precancer lesions (both LSIL and HSIL) showed moderate STAT3 DNA binding, whereas, cancer biopsies revealed a prominent STAT3 activity." (PMID 20977777, 2010). "These circumstances necessitate the search for novel targeted and more effective therapies for these cancers and STAT3 signalling represents an attractive target." (PMID 19127268, 2009).
cancer (continued). "Given these oncogenic functions of STAT3, directly targeting the constitutive activation of the STAT3 pathway represents a potential therapeutic option in cancers with constitutively active STAT3." (PMID 19127268, 2009). "Stat3 is constitutively active in many different cancers including prostate, breast, lung, head and neck, colon, liver, and pancreas as well as in multiple myeloma and large granular lymphocytic leukemia." (PMID 19274102, 2009). "EP300, ISGF3G, STAT1, and STAT3 are up regulated in 8/13 of cancer models, while ATM, BAX, BCL2L11, HTATIP2, LGALS3, MAPK1, and TP73L are down regulated in half of cancer models." (PMID 19402918, 2009). "Using our STAT-Finder program, we identified eight novel STAT3 target genes among a group of genes that are highly expressed in cancer cells." (PMID 19730699, 2009). "Stat3, a regulator of cell survival, wounding and metabolism is constitutively activated by phosphorylation in most cancers." (PMID 19440292, 2009). "We integrated microarray data obtained from the expression module map of genes up-regulated in cancer and data derived from the A549 cells over-expressing a constitutively active form of STAT3." (PMID 19730699, 2009). "HA participates in cancer progression and metastasis, and also modulates the effects of C1q and C6, along with STAT3 activation." (PMID 19484134, 2009). "This is of particular interest in drug development strategies as both CXCR4 and STAT3 antagonisms have been proposed as broad spectrum target in cancer therapy." (PMID 19455144, 2009). "There have been several strategies to inhibit the STAT3 pathway as a therapeutic approach in treating cancers, such as by using small molecules and DNA decoys." (PMID 19127268, 2009). "In many cancers, STAT3 is constitutively activated, and aberrant STAT3 signalling is implicated as an important process in malignant transformation and induction of angiogenesis." (PMID 19455144, 2009). "In a different setting, contact-dependent activation of STAT3 has been also demonstrated in normal and cancer breast cells." (PMID 19718269, 2009). "Although more work is required to fully understand mechanisms of anticancer action of glucosamine, this study provides the basis for the potential application of glucosamine as an inhibitor of STAT3 signaling pathway in cancer cells." (PMID 19744341, 2009). "HA also participates in cancer invasion, suggesting that HA activates STAT3 for promoting cancer metastasis." (PMID 19484134, 2009). "Using STAT-Finder, we have identified a list of STAT3 target genes that are over-expressed in human cancer cells." (PMID 19730699, 2009). "Low-to-moderate STAT3 activation was present in normal ovaries, benign and borderline tumours as well as low- to high-grade carcinomas but the status of activated STAT3 was significantly different between the normal, benign, borderline and malignant groups." (PMID 19088723, 2009). "Constitutive activation of signal transducer and activator of transcription 3 (Stat3) signaling pathway plays an important role in several human cancers." (PMID 18939995, 2008). "Activated Stat3 promoting cancer survival and proliferation has been demonstrated in several cancers." (PMID 18939995, 2008). "IL-6 activates Stat3, which has previously been demonstrated to activate the transcription of several anti-apoptotic genes and to contribute to apoptosis resistance in cancer cells." (PMID 18270592, 2008). "Constitutive activation of Stat3 signaling pathway is frequently detected in several types of human cancers." (PMID 18939995, 2008). "In a variety of human cancers, defects in these signaling pathways or persistent presence of up-stream activators would lead to constitutive activation of Stat3 and tumorgenesis." (PMID 18939995, 2008). "To further investigate the contribution of single cell analysis to cellular signaling studies, we turned to a less complex signaling pathway, the role of STAT3 in cancer cell proliferation and apoptosis suppression." (PMID 18673568, 2008).
cancer (continued). "Specifically, STAT3 is constitutively activated in many cancer cell lines, and reduction in STAT3 levels or activity (through RNAi or inhibitors of the JAK/STAT pathways) have been shown to result in growth arrest and apoptosis." (PMID 18673568, 2008). "The constitutive activation of Stat3 has been frequently detected in various types of human cancers." (PMID 17311011, 2007). "In a variety of human cancers, the imbalance among these signaling pathways leads to constitutive activation of Stat3 that is sufficient to induce cell tumorgenesis." (PMID 17598902, 2007). "Dysregulation and constitutive activation of STAT3 have been found in numerous primary cancers such as lymphomas, leukemias, multiple myelomas, prostate, breast, lung, head and neck, melanoma, pancreas, ovary and gastric cancer cells." (PMID 17683579, 2007). "Activation of Stat3 usually leads to the expression of downstream genes, Bcl-xL, survivin, and Mcl-1, that are important for cancer cell survival and chemoresistance." (PMID 17311011, 2007). "Inhibition of constitutively active Stat3 can induce apoptosis and inhibit cancer cell growth, indicating constitutive Stat3 signaling is required for cancer cell survival and growth." (PMID 17311011, 2007). "Other methods that targets the Stat3 signaling pathway in cancer cells have also been explored, which include using anti-sense RNA, siRNA, small molecules and decoy-oligos." (PMID 17311011, 2007). "Unlike in normal cells and tissues, the constitutively activated STAT3 has been observed in a wide variety of human cancer cell lines and primary tumors." (PMID 17683579, 2007). "It has been shown that interference of the Stat3 signaling pathway leads to cancer cell apoptosis and proliferation prohibition." (PMID 17598902, 2007). "The frequencies of elevated p-Stat3 (Ser727) in both types of cancer tissues examined were very similar to the frequencies of p-Stat3 (Tyr705), 20.8% and 24.0%, respectively." (PMID 17311011, 2007). "Stat3 has been classified as a proto-oncogene and constitutive Stat3 signaling appears to be involved in oncogenesis of human cancers." (PMID 17598902, 2007). "This implied that activation of Stat3 promotes the expression of antiapoptotic genes in these two types of cancers." (PMID 17311011, 2007). "Targeting the constitutive Stat3 pathway has shown promise in inducing cancer cell death and restricting tumor growth." (PMID 17598902, 2007). "Activation of Stat3 has been shown to enhance cell survival and proliferation of cancer cells and render them resistant to chemotherapeutic drugs and stress through the activation of survival genes and cell-cycle regulated genes." (PMID 17598902, 2007). "Elevated Stat3 phosphorylation at Ser residue 727 (Ser727) was also detected in endometrial (18.3%, 11/60) and cervical (23.0%, 24/104) cancer tissues and cell lines (HT3, RL95-2 & Hec-1B)." (PMID 17311011, 2007). "Elevated levels of Stat3 activity have been observed in a number of human cancers and cancer cell lines." (PMID 16603078, 2006). "Elevated Stat3 activity has been observed in numerous spontaneous and experimentally established mammalian cancers, demonstrating a critical role in tumorigenesis." (PMID 16603078, 2006). "STAT3 blockade has been found to lead to apoptosis in a number of carcinoma cell lines; such a situation would confound our invasiveness studies." (PMID 16804520, 2006). "Only more extensive abrogation of STAT3 signalling compromises carcinoma cell survival and proliferation." (PMID 16804520, 2006). "The signaling pathways Jak2/STAT3 as well as Src kinase signaling have been discussed to contribute to apoptosis sensitivity of carcinoma cells including HCC." (PMID 17014711, 2006).
cancer (continued). "In cancers, including PC, STAT3 promotes cell survival, progression, angiogenesis, and metastasis." (PMID 41596531, 2026). "In addition, they inhibit apoptosis by the SDF-1/CXCR4 axis, and promote cancer stemness by IL-6/STAT3/Notch signalling." (PMID 41476776, 2026). "Additionally, high-dose acetaminophen has been shown to inhibit cancer stem cell activity by suppressing the STAT3 signaling pathway, offering another plausible oncologic mechanism." (PMID 41583525, 2026). "Furthermore, NET-CCDC25 interaction leads to pyruvate kinase isoform M2 (PKM2)/STAT3–mediated epithelial-mesenchymal transition (EMT) in cancer cells and eventually results in therapeutic resistance." (PMID 41480760, 2026). "Additionally, collected evidence indicates that STAT3 is typically hyperactivated in TME cells, including T cells, NK cells, Treg cells, dendritic cells, and cancer-associated fibroblasts." (PMID 41560805, 2026). "Importantly, we demonstrate that NET-DNA sensor CCDC25 is indispensable in NET-mediated treatment resistance by inducing cancer cell epithelial-mesenchymal transition via pyruvate kinase isoform M2–mediated STAT3 phosphorylation." (PMID 41480760, 2026). "The sympathetic neurotransmitter noradrenaline enhances neural invasion along dorsal root ganglion (DRG) neurites through β‐adrenergic receptor/signal transducer and activator of transcription 3 (STAT3) signaling‐mediated activation and upregulation of MMPs in cancer cells." (PMID 41556039, 2026). "Intriguingly, curcumin’s influence on STAT3 may vary based on its concentration, while it can inhibit STAT3 phosphorylation in certain cancer contexts, it may promote an anti-inflammatory phenotype in vitro by enhancing STAT3 activity at lower concentrations." (PMID 41599692, 2026). "STAT3 activation is achieved by increased phosphorylation at Tyr705, leading to enhanced expression of anti-apoptotic proteins like Bcl-2 and Mcl-1 and increased migratory, invasive, and metastatic potential of cancer cells." (PMID 41596231, 2026). "At the molecular level, the cancer-related protein STAT3 was found to be responsible for the transcriptional activation of ABHD11-AS1 in PTC; conversely, the lncRNA sponges miR-1301-3p, which causes upregulation of STAT3 mRNA levels." (PMID 41489907, 2026). "Correlation analyses confirmed a strong correlation between PD-1 and its ligands, whereas STAT1 and STAT3 expression showed no direct association with PD-L1 or PD-L2 levels in cancer samples." (PMID 42279246, 2026). "STAT3 is widely recognized as a therapeutic target in multiple cancers and has been shown to transcriptionally regulate key effector proteins such as cyclin D1, vimentin, and survivin, which are critically involved in cell proliferation, migration, and apoptosis." (PMID 41476794, 2025). "Further investigations manifested an increase in the ALDHhigh fraction with self-renewal capacity in human breast cancer cells after co-cultured with MDSCs, and the co-culture induced IL-6-dependent phosphorylation of STAT3 and activated Notch via nitric oxide (NO) in cancer cells." (PMID 39990669, 2025). "DHA and its metabolites also inhibit STAT3 phosphorylation in cancer cells." (PMID 41169395, 2025). "Additionally, PDLIM2 degrades STAT3 and the intranuclear transcription factor RelA (p65) through the ubiquitination-proteasome pathway, which exerts a cancer-inhibiting effect and thus inhibits the pathological process of lung cancer." (PMID 40476213, 2025). "Likewise, B7‐H3 overexpression‐induced spheroid formation was inhibited by cryptotanshinone, while the attenuated cancer cell stemness phenotypes observed upon silencing B7‐H3 were rescued by the transfection of STAT3C to promote STAT3 activation." (PMID 40859957, 2025). "The effects of STAT3 signaling on cancer are dual, encompassing both promotion and suppression." (PMID 40867609, 2025).
cancer (continued). "IL - 6 serves as a critical activator of STAT3 and establishes a forward-feedback loop via the IL - 6–JAK–STAT3 axis: paracrine IL - 6 binding to IL - 6R–gp130 complexes induces STAT3 activation, which in turn stimulates autocrine IL - 6 expression within cancer cells." (PMID 41000397, 2025). "Furthermore, key molecular pathways under investigation comprise epithelial-mesenchymal transition (EMT), AKT, mTOR, PI3K, and Stat3 pathways, which represent critical nodes in the regulatory networks of cancer biology." (PMID 40771926, 2025). "STAT3 mediates critical cancer processes through transcriptional regulation of survival genes." (PMID 41312415, 2025). "The integration of STAT3 inhibitors with other anticancer agents and optimizing DDSs could significantly improve treatment outcomes in cancer therapy." (PMID 40166646, 2025). "The JAK2/STAT3 pathway plays a key role in the aggressiveness of several malignant tumors." (PMID 40944417, 2025). "Interestingly, SHP-1 gene deletion (siRNA) inhibited the ability of BCPO to suppress STAT3 activation, resulting in the induction of apoptosis and abolition of the invasive potential of cancer cells." (PMID 40333803, 2025). "STAT3, a pivotal transcription factor, coordinates multiple cellular processes, notably cell growth and apoptosis, and governs an array of genes crucial for cancer cell survival, proliferation, invasion, metastasis, drug resistance and immune evasion." (PMID 40143965, 2025). "All these activities indication potential of these compounds as anti-proliferative agent in cancer cells, to concrete these findings, further investigation into natural compounds derived from C. lanceolatus as targeting agents against STAT3 is suggested by an in silico research." (PMID 40061959, 2025). "Given these strengths, anti-STAT3 mcDNA may represent a potentially effective therapeutic approach for modulating STAT3 activity in cancer." (PMID 41031165, 2025). "Also, we found that drivers of cancer cell migration and invasion, such as p‐STAT3 and N‐cadherin, were upregulated with TOMM20 overexpression and downregulated in TOMM20 knockdown cells." (PMID 39996379, 2025). "Moreover, MHC-II signalling, particularly via HLA-DR, has been implicated in promoting cancer cell migration and invasion by upregulating the expression of integrins and cell adhesion molecules and concurrently activating the JAK/STAT3 and PI3K/AKT pathways." (PMID 41281745, 2025). "Its downstream STAT3 is a key signal involved in promoting the survival of cancer cells, and activated STAT3 enters the nucleus to enhance the transcription of downstream EMT-related genes, thereby enhancing the migration, invasion, and chemical resistance of cancer cells." (PMID 40109856, 2025). "Evidence suggests that LCA contributes to cancer by lowering the performance of STAT3." (PMID 40867609, 2025). "These include differences in cancer-specific STAT3 signaling and post-translational modifications." (PMID 40075607, 2025). "Similarly, the STAT3 pathway contributes to cancer growth, survival, metastasis, and angiogenesis during tumor development." (PMID 39561105, 2025). "Our study demonstrates that SESN1&2 deficiency may cause STAT3 activation and facilitate carcinogenesis and drug resistance, making SESN1&2 reactivation a potential cancer treatment strategy." (PMID 39985075, 2025). "Melittin downregulates cancer-progressive genes by inhibiting the JAK2/STAT3 pathway." (PMID 40243485, 2025). "Moreover, these natural compounds from C. lanceolatus downregulated the expression of STAT3 downstream target proteins, indicating their potential as therapeutic agents against cancer." (PMID 40061959, 2025). "Furthermore, targeting STAT3 epigenetic modifications presents an emerging and promising approach for cancer treatment." (PMID 40166646, 2025).